NLRP3 (NLR family pyrin domain containing 3)
Diseases named in the same sentence as NLRP3 in open-access papers (continued):
Sharing a sentence is not in itself a finding about the gene and the disease.
infection (continued). "NLRP3 inflammasomes respond to various risk states of the body (including infection and metabolic disorders) after inflammatory factors (IL-1β, IL-18) are released, mainly causing lung injury." (PMID 33954183, 2021). "NLRP3 deficiency results in susceptibility to infection, suggesting that NLRP3-mediated responses contribute to the development of host protection against S. schenckii infection." (PMID 34071562, 2021). "Listeria monocytogenes, another pathogen causative of severe infections in transplant recipients and other immunocompromised individuals, induces NLRP3 activation via phagosomal membrane damage by secreting the toxin listeriolysin O." (PMID 34769275, 2021). "In conclusion, we found that pathogenic E. coli HPI infection of Yunnan Saba pigs upregulated the expression of NLRP3, caspase-1, IL-1β and IL-18 mRNA, and promoted cell membrane pore formation and nuclear DNA damage in macrophages." (PMID 33678162, 2021). "Upon infection with RNA viruses such as influenza virus, NLRP3 and MAVS associate with MFN2 in a mitochondrial membrane potential (ΔΨm)‐dependent manner." (PMID 34337844, 2021). "Direct activation of NLRP3 inflammasome has also been documented by pathogenic fungal products derived from Candida albicans and Aspergillus, and infections with these pathogens are an important cause of morbidity and mortality among HSCT recipients." (PMID 34769275, 2021). "Chromatin accessibility for pro-inflammatory and infection-associated genes such as Il1b, Il6, Nlrp3, Itgam (Cd11b), CD80, CD14, Fos, and Jun were also increased in infected AMs and IMs (cluster 5)." (PMID 34292313, 2021). "The NLRP3 inflammasome is activated when increased fungal load in the infection microenvironment drives down glucose levels, thereby causing glucose starvation in macrophages." (PMID 32750090, 2020). "A wide range of endogenous DAMPs and exogenous PAMPs can trigger NLRP3 inflammasome activation, making it the perfect candidate for inflammasome-mediated responses during surgical injury and associated infection." (PMID 32508525, 2020). "The mechanism for canonical NLRP3 activation during S. Typhimurium infection has yet to be fully elucidated, although reduced glycolytic flux caused by infection in macrophages has been proposed as a trigger." (PMID 32185892, 2020). "The innate immune system is essential for detection and elimination of bacterial pathogens, inflammatory response caused by Brucella controls infection and be a protective effect in host, inflammasome NLRP3 complex was activated during Brucella infection." (PMID 33414782, 2020). "The mortality rate of NLRP3 or ASC gene-deficient mice after infection with Cryptococcus neoformans was higher than that of wild-type mice, and the bacterial load in the lung tissues of NLRP3-deficient mice was significantly higher than that of wild-type mice." (PMID 32148650, 2020). "Following traumatic insult and associated pathogen infection, innate immunity is activated during the perioperative period, especially the NLRP3 inflammasome in macrophages." (PMID 32508525, 2020). "In contrast to priming “signal 1,” functional activation of the synthesized Nlrp3 inflammasome is mediated by “signal 2,” which is delivered by exogenous or endogenous danger-associated products related to infection, cell activation, or cell/tissue damage." (PMID 32313108, 2020). "The NLRP3-mediated inflammasome is the most studied inflammasome and has been linked not only to the initial response to pathogenic infections, but also to a number of chronic inflammatory pathologies." (PMID 33198300, 2020). "Inhibition of NLRP3 or caspase-1 during infection of macrophages with the severe TB causing isolate (6C4) also decreased IL-1β secretion." (PMID 32327653, 2020). "N. brasiliensis infection caused increased levels of pro–IL-1β within alveolar Mφs; however, this infection-induced response was unaffected by NLRP3 deficiency." (PMID 31586037, 2019).
infection (continued). "Our observation that the early neutrophilic response was enhanced in NLRP3-deficient mice was contrary to the expectation that infection with N. brasiliensis would result in inflammasome activation." (PMID 31586037, 2019). "Nlrp3, Asc, Caspase-1 KO mice and/or Nlrp3 Aim2 double KO mice were more susceptible to infection with A. fumigatus, C. albicans, C. neoformans, P. brasiliensis and S. schenckii." (PMID 29522806, 2019). "Although infection, tissue damage, and metabolic dysregulation can trigger activation of the NLRP3 inflammasome, the host can control against damage caused by the resulting inflammation via a mechanism of negative regulation." (PMID 31174550, 2019). "In that study, MCC950 treatment and caspase-1/11 deficiency was able to phenocopy Nlrp3−/− mice during infection." (PMID 31586037, 2019). "In response to damage or infection, NLRP3, apoptosis-associated speck-like protein containing a caspase recruitment domain, and procaspase-1, via protein-protein interactions, assemble a multi-protein complex often termed as the NLRP3 inflammasome." (PMID 30914955, 2019). "To address this issue, we isolated pDCs from YM-infected WT and gene deficient (Aim2−/−, Nlrp3−/−, Casp1−/−, Il1r1−/−, and Mavs−/−) mice at 18 h post YM infection and assessed mRNA expression levels of SOCS1, IFN-α and IFN-β." (PMID 30470758, 2018). "Infection of mice deficient in NLRP3, ASC, and caspase-1/11 resulted in decreased production of IL-18 and reduced IFN-γ in serum." (PMID 30105037, 2018). "NLRP3 has been widely shown to be activated during infections with pathogenic microbes by interleukin-1β (IL-1β)." (PMID 30013955, 2018). "NLRP3-deficient mice were also more susceptible to infection with Citrobacter rodentium than wild-type mice, suggesting that NLRP3 expression has a protective effect on the intestinal epithelium." (PMID 30588399, 2018). "The P2X7 receptor has been implicated in controlling infection by intracellular microorganism via a Th1/Th17 immune response, dependent on the NLRP3 inflammasome." (PMID 30038612, 2018). "The role of the NLRP3 inflammasome in pathogenic infections, such as those caused by Pneumococcus, Helicobacter pylori, Neospora caninum, and Mycobacterium tuberculosis has been demonstrated." (PMID 29490620, 2018). "Although NLRP3 inflammasomes play critical role in combating against infections, aberrant activation of this inflammasome has been linked to many inflammatory diseases." (PMID 29375379, 2017). "Mice lacking TLR12, the TLR-induced adaptor proteins MyD88 or UNC93B1 and the inflammasome proteins NLRP3 or ASC all exhibit a high susceptibility to Toxoplasma infection during the early stage of the infection due to an impaired innate immune response." (PMID 28701773, 2017). "In contrast, one study has reported that NLRP3 deficient mice infected with L. amazonensis are more susceptible to infection, although L. amazonensis infected mice fail to heal in the presence or absence of the NLRP3 inflammasome." (PMID 28192528, 2017). "The NLRP3 inflammasome plays a critical role in mediating the innate immune defense against pathogenic infections, but aberrant activation of NLRP3 inflammasome has been linked to a variety of inflammatory diseases." (PMID 29375379, 2017). "The authors reasoned that the increased mortality seen in mice deficient in NLRP3 inflammasome components was due to impaired viral clearance, as viral titers remained elevated late in infection." (PMID 28740490, 2017). "Further, following intransal instillation of a 50% lethal dose of Ft LVS nearly all Nlrp3-/- mice survived while all of the IL-1R-/- or other inflammasome component-deficient mice succumbed to infection." (PMID 27926940, 2016). "After Ft LVS infection IL-1β and IL-18 levels are similar between Aim2- and Nlrp3-deficient mice, yet mice deficient in Aim2, ASC, or caspase-1/11 do not reproduce the survival phenotype of Nlrp3 mice." (PMID 27926940, 2016).
infection (continued). "gingivalis strain CCUG25226 was used to study the mechanisms underlying the regulation of HGF NLRP3 expression by the infection of high-glucose-treated P. gingivalis (HGPg)." (PMID 28083517, 2016). "IL-1 is important for neutrophil recruitment during Ft LVS infection, but Nlrp3-deficient mice have increased neutrophil numbers despite diminished IL-1β." (PMID 27926940, 2016). "In PAM3CSK4-primed THP-1 cells, super-infection with HAdV-C5 causes endosomal lysis and cathepsin B release, which is accompanied with mitochondrial stress, ROS formation, NLRP3 inflammasomes, and IL-1β maturation and secretion." (PMID 27636895, 2016). "To unravel the functional activity of either NLRP3 or NLRC4 in these infection models, we assessed Nlrp3–/– or Nlrc4–/– mice for susceptibility to either infection and inflammasome activity." (PMID 26972847, 2016). "Others have reported the activation of NLRP3 complexes and recruitment of caspase-1, together with IL-18/IL-1β release, in primary microglia and in macrophages stimulated by infection-associated agents." (PMID 28096568, 2016). "Increased IL-1β and activation of NLRP3 inflammasomes were also detected during infection of flaviviruses associated to CNS, including JEV and WNV." (PMID 27610098, 2016). "The interleukin (IL)-1β, processed by the NLR family pyrin domain containing 3 (NLRP3) inflammasome, has been identified as a target for pathogenic infection of the inflammatory response." (PMID 28083517, 2016). "The inflammasome NLRP3 is activated by pathogen associated molecular patterns (PAMPs) during infection, including RNA and proteins from influenza A virus (IAV)." (PMID 27283237, 2016). "In C. albicans, it has been demonstrated that in a disseminated model of infection, loss of NLRP3 leads to increased mortality and an increased fungal burden in several organs, such as the kidney, lung, and liver." (PMID 26204108, 2015). "The second signal required for NLRP3 activation consists of a broad range of infection or stress-associated signals, and due to the diverse nature of these signals, it is unlikely that direct interactions with NLRP3 would induce its activation." (PMID 26247017, 2015). "Collectively, these results provide convincing evidence that Leishmania GP63 is the causative factor for an impaired IL-1β production by the NLRP3 inflammasome complex, which was observed after infections with Leishmania parasites prior to cell stimulation." (PMID 26114647, 2015). "This is consistent with a recent publication showing that the acellular vaccine protects NLRP3 deficient mice from challenge infections." (PMID 25198773, 2014). "The NLRP3−/− and caspase-1−/− macrophages demonstrated a marked deficiency in the control of infection, as the number of amastigotes and the frequency of infected cells were even higher than in the susceptible MyD88−/− macrophages." (PMID 24098823, 2013). "Caspase-1 activation and the processing/release of IL-1β were completely inhibited in the infection of NLRP3- and ASC-deficient BMMs, whereas inhibition was marginal in NLRC4-deficient cells." (PMID 23357873, 2013). "To further investigate the mechanisms responsible for caspase-1 activation by V. parahaemolyticus, we next examined caspase-1 activation in NLRP3- or NLRC4-deficient macrophages in response to infection with V. parahaemolyticus." (PMID 23357873, 2013). "In mice, NLRP3 mediates inflammation and production of cytokine and chemokines during influenza A infection and NLRP3 is important for restricting the infection, as evidenced by the finding that NLRP3-deficient mice show enhanced mortality compared to wt mice." (PMID 23435233, 2013). "On the other hand, the release of LDH induced by infection with V. parahaemolyticus was partially inhibited in infected NLRP3-deficient cells." (PMID 23357873, 2013).
infection (continued). "To identify the effector genes, we further introduced a deletion in the h2, h3 or h4 region and examined NLRC4 inflammasome activation after infection with the h2, h3, or h4 mutants as well as the h1 mutant in NLRP3-deficient BMMs." (PMID 23357873, 2013). "Using a mouse model of infection, we identified a central nervous system (CNS)-intrinsic requirement for the NLRP3 inflammasome and IL-1β signaling in limiting WNV associated disease within the CNS." (PMID 23209411, 2012). "Gsdme deficiency increased susceptibility to ST infection, like Nlrp3 deficiency." (PMID 41360763, 2025). "Caspase-11 and NLRP3 deficiency diminished the reduction of TMRM fluorescence upon infection." (PMID 40034692, 2025). "GO analysis also showed multiple NLRP3-associated inflammatory responses upon infection." (PMID 40143222, 2025). "Moreover, pulmonary IL-6 level upon infection significantly decreased in mice deficient in caspase-11 or NLRP3." (PMID 40034692, 2025). "Pathogens such as periodontal bacteria have been linked to NLRP3 activation in arteries, implying that infection control may indirectly reduce pyroptosis within plaques." (PMID 40832143, 2025). "Interestingly, while infection induced a transient rise in neutrophil numbers at 1 hpi in both wild-type and Nlrp3-deficient larvae, only wild-type larvae showed a marked reduction in neutrophil counts at 3 and 6 hpi." (PMID 41360763, 2025). "Nonetheless, uncontrolled inflammasome activation may lead to detrimental responses in the context of infections and other NLRP3-associated diseases." (PMID 40307577, 2025). "N. caninum infection induces the release of IL-1β and IL-18, cleaved caspase-1, and cell death in mouse bone marrow-derived macrophages, while infection of mice deficient in NLRP3, ASC, and caspase-1/11 leads to a decrease in IL-18 production and an increase in IFN-γ in the serum." (PMID 41357231, 2025). "The NLRP3 inflammasome, in particular, emerges as a central integrator of metabolic, mitochondrial, ionic, and damage-associated signals, whose dysregulation drives progression from localized infection to systemic inflammation and multiorgan dysfunction." (PMID 40558557, 2025). "Interestingly, the effects of a temporal inhibition of the NLRP3 function during pathogenic IAV infection have shown that NLRP3 plays a dual role in infection." (PMID 41011440, 2025). "To investigate whether this correlation between NLRP3 activation and disease exacerbation implies a cause-and-effect relationship, we performed infections in transgenic mice expressing the human ACE2 receptor." (PMID 38838044, 2024). "Infection with lentivirus encoding all three tested proteins induced significant pyroptosis-like cell death in comparison to control lentivirus with ORF3a and E proteins causing the strongest effect which was partially reduced by NLRP3 inhibition with MCC950." (PMID 38664396, 2024). "Thus, in this context, the NLRP3 inflammasome plays both a protective role early in infection and a pathogenic role later in infection." (PMID 38662771, 2024). "As commented above, the NLRP3 inflammasome activation is vital in the innate immune response to pathogenic infections, promoting the release of pro-inflammatory interleukins to facilitate the recruitment of immune cells for containing the infection’s spread." (PMID 39434905, 2024). "However, as infection progresses, bone destruction becomes unavoidable, with NLRP3 contributing to osteoblast death and subsequent bone loss at the infection site." (PMID 39201755, 2024). "In mice infected with murine beta coronavirus A59, a ketogenic diet resulting in mild physiological ketosis prevented infection-induced weight loss and hypoxemia, improved survival, and reduced the expression of the NLRP3 inflammasome and pro-inflammatory cytokines (IL-1β, TNFα, IL-6)." (PMID 37934800, 2024).
infection (continued). "Furthermore, to confirm that NLRP3 or AIM2 is important for inflammasome activation during infection with A. actinomycetemcomitans, as reported in previous studies, we used BMDMs from wild-type, NLRP3-deficient, or AIM2-deficient mice." (PMID 39143049, 2024). "The presence of the bat-specific splice variant of NLRP3 was also noted in Myotis davidii (M. davidii) (Yangochiroptera suborder), implying that dampened NLRP3 activation is a strategy employed by multiple bat species in response to infection." (PMID 39599847, 2024). "Our results showed a positive modulation of the NOD1, NOD2, and NLRP3 genes after 24 h of co-culture, suggesting that in the early stages of infection, the transcription of these genes may be associated with the transcription of the TLR genes." (PMID 38248981, 2024). "However, the secretion of IL-18 induced by infection with all the strains was significantly suppressed in the NLRP3- or ASC-deficient macrophages." (PMID 37910490, 2023). "Specific NLRP3 targeting might allow the production of IL-1β by other inflammasomes and reduce the risk of infections associated with the use of anakinra which will block IL-1 driven by any inflammasome." (PMID 36661317, 2023). "NLR pyrin domain containing 3 (NLRP3) inflammasome is a multiprotein complex composed of ASC, NLRP3, and caspase-1, which serves as a central innate immune sensor triggered by endogenous “danger” signaling in response to pathogenic infection, metabolic dysregulation, and tissue damage." (PMID 37082194, 2023). "The wild-type mice showed high numbers of neutrophils at the site of infection in the ear, that may be due to high IL-1β compared to deficient NLRP3 inflammasome mice." (PMID 37276232, 2023). "On the other hand, it has been reported that NLRP3-deficient mice seem to be protected against cerebral and placental malaria, as well as the severity of leishmaniasis caused by L. braziliensis and L. major Seidman strain infections." (PMID 38124741, 2023). "Interestingly, the infection-related increase of LCN2 was diminished in mice that displayed additional Nlrp3 or Gsdmd deficiency." (PMID 37240031, 2023). "Our results confirmed that LPS infection indeed caused acute inflammatory damage in mice lung, accompanying with the enhancement of IL-1β contents and the activation of the NLRP3 inflammasome in lung tissue and macrophagocyte, all of which were remarkably ameliorated by PR treatment." (PMID 36046826, 2022). "To further investigate the mechanisms responsible for Caspase-1 activation by S. Enteritidis GalE protein, we monitored the activation of Caspase-1 in Nlrp3−/− and Nlrc4−/−-deficient BMDMs in response to infection with different mutant strains of S. Enteritidis." (PMID 35630356, 2022). "However, it is important to note that abnormal activation of NLRP3 inflammasome is frequently associated with tissue injury during infection." (PMID 35330457, 2022). "Although the overactivation of NLRP3 inflammasome and release of cytokines can cause tissue and organ damage, it is demonstrated that inflammasome and IL-1β can also provide protections in the acute phase of multiple pathogens infection." (PMID 36618363, 2022). "Infection of NLRP3- or NLRC4-deficient bone marrow-derived macrophages (BMDMs) with Salmonella revealed that inhibition of Caspase-1 by GalE was dependent on the NLRP3 inflammasome." (PMID 35630356, 2022). "However, NLRP3-deficient mice also display significant lung damage following infection and reduced IL-1β production." (PMID 36580480, 2022). "This stimulates NOD, LRR, and pyrin domain-containing protein 3 (NLRP3) inflammasome signaling, causing inflammatory cytokines and chemokines to migrate to the site of infection, followed by polymorphonuclear leukocyte invasion in the vaginal epithelial lamina propria." (PMID 35832797, 2022). "Similarly, the NLRP3 inflammasome plays a protective role in the early phases of the infection and has pathogenic effects in the late stages." (PMID 33766561, 2021).